Y_RNA (Y RNA )
Gene: Miscellaneous RNA gene on chromosome 7 (73,011,144 to 73,011,245, forward strand). Ensembl gene ENSG00000201282.
Homologues: Orthologues: chimpanzee Y_RNA (99% identical), pig Y_RNA (75% identical). Paralogues in human: Y_RNA (100% identical), Y_RNA (97% identical), Y_RNA (93% identical), Y_RNA (92% identical), Y_RNA (90% identical), Y_RNA (89% identical), Y_RNA (87% identical), Y_RNA (85% identical), RNY3 (84% identical), RNY3P12 (84% identical), Y_RNA (84% identical), RNY3P1 (83% identical), and 98 more.